ESPL1 (extra spindle pole bodies like 1, separase)
Diseases named in the same sentence as ESPL1 in open-access papers (continued):
Sharing a sentence is not in itself a finding about the gene and the disease.
liver cancer (3 papers, 2023 to 2025). An epithelial or non-epithelial malignant neoplasm that arises from the liver. "We found that the highest expression of ESPL1 was in lymphoma, leukemia, neuroblastoma, and liver cancer cell lines." (PMID 37006282, 2023). "have also detected high expression of the ESPL1 gene in liver cancer tissues." (PMID 40248196, 2025). "Our findings indicate that serum levels of ESPL1 may serve as a valuable indicator of the severity of HBV-HCC, facilitating the distinction between small liver cancers and cirrhotic nodules." (PMID 40248196, 2025).
lung adenocarcinoma (3 papers, 2020 to 2022). A carcinoma that arises from the lung and is characterized by the presence of malignant glandular epithelial cells. "High expression of ESPL1 mRNA was also significantly associated with poor OS only in patients with lung adenocarcinoma [p = 1.2 × 10−5, HR = 1.69 (95% CI, 1.34–2.15)]." (PMID 36359523, 2022). "Among the patients with lung squamous cell carcinoma and lung adenocarcinoma, high expression of ESPL1 was associated with poor OS and PFS [p = 4.1 × 10−12, hazard ratio (HR) = 1.57 (95% CI, 1.38–1.78) and p = 2.1 × 10−9, HR = 1.78 (95% CI, 1.47–2.15), respectively]." (PMID 36359523, 2022). "Both for lung squamous cell lung carcinoma and lung adenocarcinoma, ESPL1 and Timeless were highly co-expressed with a strong correlation." (PMID 36359523, 2022). "However, the association of ESPL1 with prognosis and immune infiltration in lung adenocarcinoma (LUAD) has not yet been explored." (PMID 35814478, 2022).
ovarian carcinoma (3 papers, 2021 to 2024). A malignant neoplasm originating from the surface ovarian epithelium. "Further work is required to resolve the conflicting roles of ESPL1 in cancer and determine its functions in cancers including the ovarian cancer." (PMID 34143800, 2021).
and kidney cancers (2 papers, 2011 to 2021). "The COSMIC database indicates that somatic mutations in the ESPL1 gene was related to human lung and kidney cancers." (PMID 34856998, 2021). "Correlative studies have reported the loss or decrease in Separase expression levels caused by somatic mutations in the ESPL1 gene in human lung and kidney cancers (Catalogue of Somatic Mutations in Cancer, COSMIC database;)." (PMID 21799785, 2011).
cervical cancer (2 papers, 2023 to 2024). A primary or metastatic malignant neoplasm involving the cervix. "RNA-Seq analysis revealed that overexpression of the HPV16/18 E6/E7 genes upregulated GP6, CD36, HDAC6, ESPL1, and DNMT3B among the differentially expressed genes (DEGs) associated with cervical cancer." (PMID 39411320, 2024). "Through cross-screening of HPV infection-related DEGs and cervical cancer-related DEGs, we identified five significantly upregulated DEGs, e.g., GP6, CD36, HDAC6, ESPL1, and DNMT3B." (PMID 39411320, 2024).
chronic myeloid leukemia (2 papers, 2016 to 2022). "In addition, it was reported that c-MYB is a crucial transcriptional regulator that modulates the expression of ESPL1 in chronic myeloid leukemia." (PMID 35814478, 2022).
gastric cancer (2 papers, 2024 to 2025). A primary or metastatic malignant neoplasm involving the stomach. "Inhibiting ESPL1 could enhance the sensitivity of gastric cancer (GC) cells to apatinib treatment." (PMID 41268575, 2025).
leukemia (2 papers, 2011 to 2023). A malignant (clonal) hematologic disorder, involving hematopoietic stem cells and characterized by the presence of primitive or atypical myeloid or lymphoid cells in the bone marrow and the blood.
lymphoma (2 papers, 2011 to 2023). A malignant (clonal) proliferation of B- lymphocytes or T- lymphocytes which involves the lymph nodes, bone marrow and/or extranodal sites. "We failed to observe any tumors or any other obvious abnormalities in the ESPL1+/hyp mice during their life span though about 5% of the control cohort of littermate WT mice developed sarcomas and appeared sick (possible lymphomas) and had to be sacrificed within a 2 year time frame." (PMID 21799785, 2011). "Of interest is also the fact that the Separase mutant mice alone (ESPL1+/hyp) do not have a lymphoma phenotype." (PMID 21799785, 2011).
prostate carcinoma (2 papers, 2024). A carcinoma that arises from epithelial cells of the prostate gland. "ESPL1, a cysteine endopeptidase, was an oncogene and its overexpression was reported in a broad range of human tumors, including breast, brain, and prostate cancers." (PMID 38402402, 2024). "First, a previous study reported that ESPL1 was an effective predictor of overall survival, recurrence-free survival and metastasis-free survival in prostate cancer patients, and similar findings have been reported for UCEC." (PMID 38813236, 2024).
atherosclerosis (1 paper, 2022). A disease characterized by the build-up of fatty material and calcium deposition in the arterial wall resulting in partial or complete occlusion of the arterial lumen. "Endou, Hdac7, Senp1, Olfr286, Olfr285, Nckap5l, Smarcd1, Lima1, Fam186a, and Espl1 are probable candidate genes for distal Chr15 atherosclerosis QTL (Ath53)." (PMID 36078077, 2022).
bile duct cancer (1 paper, 2023). "Moreover, the expression of ESPL1 was low in liposarcoma, bile duct cancer, and head and neck cancer cell lines." (PMID 37006282, 2023).
Cirrhosis (1 paper, 2025). A chronic disorder of the liver in which liver tissue becomes scarred and is partially replaced by regenerative nodules and fibrotic tissue resulting in loss of liver function. "Conversely, among patients with hepatitis and cirrhosis who were positive for PIVKA-II, 2 out of 23 (8.7%) exhibited ESPL1 positivity." (PMID 40248196, 2025). "In patients with hepatitis and cirrhosis who were positive for AFP, no ESPL1 positivity was detected." (PMID 40248196, 2025).
colorectal cancer (1 paper, 2023). A primary or metastatic malignant neoplasm that affects the colon or rectum. "Therefore, we determined the connection between ESPL1 expression and these three small molecule inhibitors using colorectal cancer patient-derived organoids." (PMID 37006282, 2023). "Through organoid drug sensitivity testing, we confirmed that the expression of ESPL1 was statistically linked with PHA-793887, PAC-1, and AZD-7762, and that the expression of ESPL1 in colorectal cancer patient tissues may indicate the use of these drugs." (PMID 37006282, 2023).
Cornelia de Lange syndrome (1 paper, 2020). A rare syndrome characterized by low birth weight, delayed growth, intellectual disabillity, behavioral problems, and a distinctive facial appearance (thin, arched eyebrows, low set ears, small teeth, and small nose). "Variants in genes encoding various structural or functional components of the cohesin complex, including RAD21, SMC1A, SMC3, BRD4, STAG1/2, NIPBL, HDAC8, WAPL, ANKRD11 and in single individuals PDS5A and ESPL1, have been implicated in Cornelia de Lange Syndrome (CdLS)." (PMID 32193685, 2020).
diffuse intrinsic pontine glioma (1 paper, 2023). A neuroglial tumor that arises from the middle portion of the brain stem. "GSK-J4 is thought to be effective in diffuse intrinsic pontine glioma (DIPG), and the drug sensitivity of GSK-J4 is enhanced with increased expression of ESPL1." (PMID 37006282, 2023).
female infertility (1 paper, 2022). Diminished or absent ability of a female to achieve conception. "A deregulatory mutation into separin encoded by Espl1 at early embryonic period caused primordial germ cell depletion by apoptosis during embryonic oogenesis, which led to female infertility." (PMID 35600599, 2022).
influenza (1 paper, 2023). An acute viral infection of the respiratory tract, occurring in isolated cases, in epidemics, or in pandemics; it is caused by serologically different strains of viruses (influenzaviruses) designated A, B, and C, has a 3-day incubation period, and usually lasts for 3 to 10 days. "ESPL1, encodes a key protease needed to initiate anaphase, and has not been previously reported as being elevated in influenza or MODS; however, there are studies suggesting a role in cell cycle dysregulation during influenza infections." (PMID 37533854, 2023).
malignant glioma (1 paper, 2021). A grade III or grade IV glioma arising from the central nervous system. "The purpose of this study was to reveal the potential mechanisms of ESPL1-mediated malignant glioma progression." (PMID 34512713, 2021).
medulloblastoma (1 paper, 2024). A malignant, invasive embryonal neoplasm arising from the cerebellum. "However, there is no available AD-related information for the ESPL1, KIF20A, SPRR2G, and SPRR3 genes, which instead have associations with various cancers, including adenocarcinoma, medulloblastoma, tongue cancer, and pancreatic cancer, respectively." (PMID 39766348, 2024).
pituitary tumor (1 paper, 2023). A benign or malignant neoplasm affecting the pituitary gland. "Diurnal rhythm of PER2 parallels those of cell cycle genes (Ccnb2, Cdc20 and Espl1) in pituitary tumors, supporting PER2 as a driver of rhythmicity in these cell cycle genes and implicating a diurnal rhythm in cell cycle." (PMID 37215573, 2023).
renal cell carcinoma (1 paper, 2021). "One partner gene of ESPL1, PTTG1, was proved to be an oncogene in renal cell carcinoma and other cancer types." (PMID 34856998, 2021).
sarcoma (1 paper, 2011). A usually aggressive malignant neoplasm of the soft tissue or bone.
cancer (34 papers, 2011 to 2025). A tumor composed of atypical neoplastic, often pleomorphic cells that invade other tissues. "Based on STRING analysis, MEIKIN is implicated in chromosome segregation and cell cycle regulation, through interactions with key proteins such as SGO1, SGO2, PLK1, and ESPL1, all of which are known to play critical roles in cancer-associated pathways." (PMID 41463182, 2025). "ESPL1 also participates in the occurrence and development of other human cancers, which is associated with reduced patient survival." (PMID 41268575, 2025). "The results revealed that ESPL1 expression was significantly associated with critical cancer-related pathways including cell cycle (R = 0.33), proliferation (R = 0.31), metastasis (R = 0.31), and DNA damage response (R = 0.31)." (PMID 41268575, 2025). "Understanding the transcriptional regulation of oncogenic drivers like ESPL1 is therefore crucial for uncovering potential molecular mechanisms underlying cancer aggressiveness and for identifying novel therapeutic targets." (PMID 41268575, 2025). "This study also revealed that ESPL1 gene expression is closely associated with quiescent and cancer invasion and metastasis." (PMID 41268575, 2025). "The overactivated of ESPL1 linked to cancer and genome instability, thus it was an ideal target for drug discovery." (PMID 38402402, 2024). "The study found that ESPL1 expression was markedly upregulated in tumorous tissues compared to normal tissues, and high expression of ESPL1 was significantly associated with poor prognosis in a range of cancers." (PMID 37006282, 2023). "Given that immunoregulatory genes are closely associated with cancer development, we evaluated the expression data of 150 immunoregulatory genes in each sample and correlated them with the expression of ESPL1." (PMID 37006282, 2023). "Overall, as a key cell cycle-associated gene, the potential role of ESPL1 in carcinogenesis and cancer development is worth investigating." (PMID 37006282, 2023). "Collectively, the findings of this study reveal that ESPL1 is associated with tumorigenesis and progression in a variety of cancers, which suggests that it is a potential prognostic marker." (PMID 37006282, 2023). "Using the optimal cutoff value, we found that high expression of ESPL1 was significantly associated with poor prognosis in 18 different types of cancer." (PMID 37006282, 2023). "Through multivariate analysis that integrates clinical information, ESPL1 remains a prognostic risk factor in multiple types of cancer." (PMID 37006282, 2023). "In conclusion, this study demonstrates the potential of ESPL1 as a cancer biomarker in various malignancies, with high expression of ESPL1 associated with worse prognosis in multiple cancer types and immune infiltration." (PMID 37006282, 2023). "ESPL1 is determined to be a novel prognostic biomarker and is associated with the malignant features in several cancers." (PMID 35873497, 2022). "ESPL1 also participates in the occurrence and development of other human cancers and is associated with reduced patient survival." (PMID 34512713, 2021). "KIF14, NUF2, and ESPL1, have been associated with poorer prognosis in various cancers." (PMID 39766071, 2024). "ESPL1 might be an immune-related predictive and diagnostic marker for BC, and the overexpression of ESPL1 played a cancer-promoting role and affected BC patients’ sensitivity to drug therapy." (PMID 38813236, 2024). "Based on these findings, we conclude that ESPL1 may have oncogenic characteristics, and high expression is associated with poorer prognosis in cancer patients." (PMID 37006282, 2023). "In addition, Cut2/PTTG, a regulator of Cut1/ESPL1, is reportedly associated with cancer, while the SAPK cascade is a key therapeutic target of inflammatory disease." (PMID 29593117, 2018). "The results revealed that ESPL1 expression was significantly elevated in most cancer types compared to their corresponding normal tissues." (PMID 41268575, 2025).